TUBB (tubulin beta class I)
Diseases named in the same sentence as TUBB in open-access papers (continued):
Sharing a sentence is not in itself a finding about the gene and the disease.
tumor (34 papers, 2005 to 2025). "Considering the lack of pan-cancer analysis of TUBB, this study aims to conduct a comprehensive exploration of the potential roles of TUBB in malignant tumor cells and its underlying mechanisms in the prediction of clinical prognosis." (PMID 38756529, 2024). "The TUBB profiles, including their expressions, mutations, relations with aggressive tumor traits, and contributions to the survival of cancer patients, have been depicted." (PMID 38756529, 2024). "Class 3 of TubB is the prominent isoform linked to neoplastic disease and has been identified as a biomarker for resistance to MT-targeting chemotherapeutics in breast and other types of solid cancer." (PMID 35008169, 2021). "It has been shown that TUBB is associated with tumor aggressiveness and resistance to chemotherapy." (PMID 35327439, 2022). "In most tumor cells, the highly expressed isoform of tubulinβ5 is encoded by the TUBB gene." (PMID 32461969, 2020). "Furthermore, the first studies reporting TUBB gene mutations were made in hamster cells and in ovarian cancer cell lines after selection by paclitaxel exposure, something that makes difficult a direct extrapolation of these findings to human tumours." (PMID 16095531, 2005). "First, we analysed the expression patterns of TUBB across different epithelial cell subtypes in both normal and tumour tissues." (PMID 40539065, 2025). "The results revealed elevated TUBB expression levels in most tumour epithelial cells, with particularly significant upregulation in EEC and IIICs." (PMID 40539065, 2025). "The MCS exhibited improved viability and a gene expression profile associated with aggressive tumor characteristics, including increased expression of genes linked to cell survival and motility, such as COL1A1, MSN, HIF1A, TUBB, and ACTB." (PMID 41516217, 2025). "First of all, we determined the expression levels of TUBB mRNA and protein in tumor tissues compared to that in normal tissues across various cancers." (PMID 38756529, 2024). "We found that TUBB was significantly correlated with various cancer characteristics, tumor immune microenvironment (TIME), drug resistance, and survival states." (PMID 38756529, 2024). "In this study, we found that TUBB was generally differentially expressed between tumor tissues and normal tissues through a full-scale pan-cancer analysis, using a series of bioinformatics approaches." (PMID 38756529, 2024). "Results showed that TUBB was found to be generally highly expressed in tumor cells more than normal cells." (PMID 38756529, 2024). "TUBA1A, DBI, and TUBB are up-regulated in tumor cells and down-regulated in periphery cells, and these are marker genes for the neoplastic cluster." (PMID 35327982, 2022). "The tubulin proteins TUBA1A and TUBB and their heterogeneity has been associated with GBM, whereas DBI maintains high proliferation rates, promoting tumor growth." (PMID 35327982, 2022). "TUBB has been shown to play various pathological roles, in which elevated levels of TUBB were observed in breast cancer tumors and tumor-adjacent normal breast tissues compared to normal breast tissues." (PMID 36140469, 2022). "Five cell types, TIMP1+M3, S100A8+N3, TUBB+Mcyl, LAMP3+DC3, and TCL1A+pDC, all of which were enriched in MSC2, were positively associated with tumor progression (FDR < 0.05)." (PMID 34659209, 2021). "We found that tumor tissues express significantly higher levels of TUBB and TUBB3 and significantly lower levels of TUBB2B, TUBB6, and TUBB7P pseudogene." (PMID 30126203, 2018). "ACT, GAPDH and TUBB, the three most commonly used reference proteins, all exhibited marked elevations in tumor samples." (PMID 27556505, 2016). "The current study identified novel citrullinated proteins, including ENO1, HSP60, KRT8, and TUBB, in tumour cells." (PMID 24099319, 2013). "Immunoprecipitation analyses verified the expression and citrullination of ENO1, HSP60, KRT8, and TUBB in the total protein lysates of the tumour cell lines." (PMID 24099319, 2013).
tumor (continued). "Notably, the activation of GALECTIN and VEGF signalling suggests that TUBB-positive cells possess immunosuppressive and pro-angiogenic capabilities, indicating their potential role in tumour progression and metastasis." (PMID 40539065, 2025). "Thorough analyses are needed to understand the intrinsic role of TUBB in tumor immunity." (PMID 38756529, 2024). "TUBB was validated as a risky factor in some cancers, and immune infiltration analyses showed it may perhaps induce immune escape in tumor cells." (PMID 38756529, 2024). "It is of interest that both molecules involved in AJs, MYL3 and TUBB, are upregulated in the tumor center, which may be important for AJs in this region." (PMID 35512017, 2022). "Additionally, collagen proteins (COL1A1, COL1A2, COL3A1, COL11A1) were linked to tumor progression and metastasis, while chaperonin-containing TCP1 (CCT) complex proteins and microtubule-associated proteins (TUBA1C, TUBB) were implicated in cytoskeletal organization and chemotherapy resistance." (PMID 40867231, 2025). "Therefore, it was deduced that TUBB might be enrolled in modulating the process of cell cycle, and thus eventually have an effect on tumor cells." (PMID 38756529, 2024). "In conclusion, we suggest that the anti-tumor drug that target the TUBB/Rho/ROCK signaling pathway may be co-treated with oral antibiotics targeting E. coli, which may activate T cells, strengthen immune protection, boost immune surveillance, and enhance sensitivity to immunotherapy in PC." (PMID 32461969, 2020). "The tumor center was characterized by a higher abundance of LMNA (two proteoforms), dihydropyriminidase-related protein (DPYSL3), tubulin beta (TUBB), myosin light chain 3 (MYL3), and galectin-1 (LGALS1)." (PMID 35512017, 2022). "TUBA1C, TUBA1B and the β-tubulin isoform TUBB were found as isoforms with the highest expression levels compared to other isoforms in BC cell lines, and TUBA1C and TUBB were overexpressed in BC tumours compared to the normal breast tissues." (PMID 35167614, 2022). "NEK2 was altered in 22.9% of analyzed tumor samples and found interacted with the α-tubulin isoforms TUBA1A, TUBA4A, the β-tubulin isoforms TUBB, TUBB4A, TUBB4B and all the γ-tubulin isoforms." (PMID 30126203, 2018). "ENO1, HSP60, KRT8, PDI, TCRβ, TUΒΒ, and VIME were identified in the tumour cell lines using 2-D WB, and immunoprecipitation verified that ENO1, HSP60, KRT8, and TUBB were expressed and citrullinated in these cell lines." (PMID 24099319, 2013). "The timepoint negative for tumor infiltration revealed several TUBB proteins that are related with cellular shape maintenance, cell polarity and EMT initiation." (PMID 40342827, 2025). "It has been indicated that TUBB mediates cell cycle, epithelial-mesenchymal transition (EMT), proliferation, metastasis, and invasion in cutaneous melanoma, possibly through the downregulation of tumor suppressor miR-339-3p." (PMID 36140469, 2022). "Here, one such therapeutic, ixabepilone, targeting the functional hub tubulin beta chain (TUBB) defined in our analyses was tested in Gp3 and SHH patient-derived xenograft (PDX) models leading to the identification of considerable anti-tumour activity in all cases." (PMID 34154646, 2021). "Analyzing expression profile of BC tumors and tumor-adjacent normal breast tissues showed upregulation of TUBA1A, TUBA1C, TUBB and TUBB3 and downregulation of TUBB2A, TUBB2B, TUBB6, TUBB7P pseudogene, and TUBGCP2 in the tumor tissues compared to the normal breast tissues." (PMID 30126203, 2018). "This article is aimed at deducing that gut and tumor microbes are related to the development of PC by stimulating TUBB/Rho/ROCK signaling, while ablation of microbes by antibiotics cotreated with inhibitors of TUBB/Rho/ROCK signaling were identified as a novel target for PC therapy." (PMID 32461969, 2020).
tumor (continued). "The three most commonly used endogenous controls in protein expression assays, ACTB, TUBB and GAPDH, all displayed significant elevations in tumor samples, indicating that these proteins may not be as reliable as expected." (PMID 27556505, 2016).
cancer (33 papers, 2007 to 2025). A tumor composed of atypical neoplastic, often pleomorphic cells that invade other tissues. "In a nutshell, using the multi-omics method, TUBB has been elucidated to be dysregulated in pan-cancers as a potential diagnostic marker." (PMID 38756529, 2024). "By collecting and handling integrative data from the TCGA, Firehose, UCSC Xena, cBioPortal, GEO, CPTAC, TIMER2.0, TISCH, CellMiner, GDSC, and CTRP databases, we explored the potential diagnostic and prognostic roles of TUBB in pan-cancers from multiple angles." (PMID 38756529, 2024). "TUBB’s underlying functions across cancers have been uncovered to some extent, providing new insights for cancer profiling in depth." (PMID 38756529, 2024). "All results mutually indicated that TUBB was wicked and may induce immune escape in cancer, causing indifferent immune responses to cancer treatments, resulting in poor clinical outcomes at last." (PMID 38756529, 2024). "The tubulin beta class I genes (TUBBs) are associated with the prognosis of many different cancers." (PMID 36872411, 2023). "From the result of PEA, TUBB might be an important external gene, which associates cancers by the interactions with amount significant pathways." (PMID 30890140, 2019). "The TUBA1C and TUBB proteins are vital components of the microtubule network and are frequently dysregulated in cancer." (PMID 40867231, 2025). "While these findings were primarily focused on cancer, the significant role of TUBB in immune modulation warrants attention." (PMID 40149558, 2025). "We found that TUBB mRNA expressions were related to the z-score of 14 newly identified cancer-related function states." (PMID 38756529, 2024). "Based on the z-scores of cell cycle, we analyzed their correlations with TUBB expressions in various cancers." (PMID 38756529, 2024). "For example, in almost every cancer the TUBB mRNA expression level was positively related to the abundance of CD4+ Th1 cells." (PMID 38756529, 2024). "Great differences in the methylation patterns of TUBB suggested the complexity of TUBB regulation and the specificity of this process among different cancer species." (PMID 38756529, 2024). "High TUBB expressions were proved to have a great impact on the prognosis of various types of cancers and would affect the sensitivity of some drugs." (PMID 38756529, 2024). "Aiming at this, we further conducted drug resistance analysis and found that TUBB played an important role in regulating chemotherapy sensitivity across cancers." (PMID 38756529, 2024). "Survival profiles of pan-cancers showed that TUBB expressions were related to many kinds of survival indicators in pan-cancers, and the relations had homogeneity." (PMID 38756529, 2024). "From immune infiltration analyses, we confirmed that TUBB plays an important role in regulating immunity across cancers." (PMID 38756529, 2024). "At transcriptional and protein level, we proved TUBB was much closer to be a risky factor for cancer." (PMID 38756529, 2024). "To identify patterns of TUBB regulations in cancers, we combined TCGA and GTEx data to expand sample sizes and gained a boxplot describing TUBB expressions in pan-cancer." (PMID 38756529, 2024). "TUBB is involved in the cancer cell cycle in a variety of cancers, and its mRNA levels is correlated with an unfavorable cancer prognosis." (PMID 38635528, 2024). "All the results highlighted the critical roles of TUBB in cancer and they contribute to further studies of TUBB-related molecular mechanisms and therapeutic development." (PMID 38756529, 2024). "TUBB had genetic changes in most cancers, and the most common alteration types were amplification and mutation." (PMID 38756529, 2024). "dianilinophthalimide showed relatively lower scores in most cancers, which demonstrated that they perhaps inhibit TUBB-mediated carcinogenic effects." (PMID 38756529, 2024). "Tubulin β class I gene (TUBB) is highly expressed in various cancers and plays several roles in carcinogenesis." (PMID 36140469, 2022).
cancer (continued). "In the present study, the intersection analysis of the KIFC1-interacted proteins and the KIFC1-correlated genes identified two genes, ASPM and TUBB, as the potential important regulatory molecules that are associated with KIFC1 for cancer cell division." (PMID 35327439, 2022). "Tubulin (TUBB) is a druggable target as it has been ascribed a role in tumorigenesis and metastasis of many cancer entities and is critically regulated by Stathmin1 (STMN1)." (PMID 35063803, 2022). "MT-interacting drugs, specifically interacting with either TubA or TubB, are widely used in the therapy of several cancer types." (PMID 35008169, 2021). "Taxanes and vincristines are two most notable chemotherapeutic drugs that were reported to induce cancer cell death by arresting the cells at mitotic phase by targeting microtubules such as TUBB at the mitotic phase." (PMID 33996900, 2021). "In this field, much attention has been given to the capacity of new anti-TubA/TubB agents to affect the autophagic process, their capacity to stimulate or inhibit the autophagic flux and to promote autophagic or apoptosis-related cancer cell death." (PMID 35008169, 2021). "We used GEPIA to extract expression data from various types of cancers in order to clarify the differential expression of TUBB in PC and other potential tumors." (PMID 32461969, 2020). "Especially, through this analysis, proteins (PPCS, PMP2, and TUBB) and metabolites (L-carnitine and PC-O (30:0)) related to the carnitine system involved in cancer plasticity were identified." (PMID 33228226, 2020). "Moreover, the GSEA analysis was conducted to excavate the biological functions of TUBB in pan-cancers." (PMID 38756529, 2024). "Also, we found that TUBB was related to many vital biological pathways, indicating its indispensable roles in cancers." (PMID 38756529, 2024). "First of all, the heatmap displayed the landscape of immune infiltration of TUBB across cancers." (PMID 38756529, 2024). "TUBB was identified as an important indicator across multiple cancers." (PMID 38756529, 2024). "To study genetic changes of TUBB in cancers, we checked the percentage of SCNA." (PMID 38756529, 2024). "Furthermore, metabolism-related pathways were analyzed systematically, and the results had satisfying consistency across cancers, indicating the functions of TUBB were highly conservative." (PMID 38756529, 2024). "In other words, TUBB might encourage the formation of immunological rejection or “immunological desert”, and play a vital role in immunity-cancer crosstalk, especially in immune escape." (PMID 38756529, 2024). "In most cancers, the mRNA expression of TUBB was significantly correlated with SNCA." (PMID 38756529, 2024). "The methylation patterns of TUBB in pan-cancers were consistent with each other." (PMID 38756529, 2024). "TUBB plays an important role in cancer progression and targeting TUBB may provide significant clues in cancer treatments." (PMID 38756529, 2024). "Generally speaking, copy number variations were commonly seen in cancer, and these could in turn affect TUBB expressions." (PMID 38756529, 2024). "Higher expressions of TUBB would result in less immune-related molecules in pan-cancer." (PMID 38756529, 2024). "However, how TUBB modulates cancer initiation and advancement in pan-cancers remains controversial." (PMID 38756529, 2024). "Therefore, TUBB may play different roles in pan-cancers, suggesting further explorations of it should be addressed." (PMID 38756529, 2024). "Hence, it is necessary to explore TUBB profiles from the perspectives of multiple cancer cells." (PMID 38756529, 2024). "Therefore, it could be concluded that TUBB CNAs were common among cancers, and it could affect TUBB expressions." (PMID 38756529, 2024). "Thus, a TUBB-related signature containing 150 significantly upregulated and 150 significantly downregulated genes that were selected by screening patients with high- or low-TUBB expressions in various cancers, was generated." (PMID 38756529, 2024).
cancer (continued). "Therefore, TUBB as a mediator, has been studied in the cancer research area." (PMID 38756529, 2024). "However, it is unclear whether the interactions among KIFC1, ASPM, and TUBB have synergistic effects on the progression of cancer." (PMID 35327439, 2022). "The frequency and impact of TubB isoforms and mutations in cancer is still not fully understood." (PMID 35008169, 2021). "CDK6 and TUBB therefore act as network “bridging nodes”, that is, nodes that connect otherwise separate regions of the network and represent proteins through which previously identified candidate cancer genes driving MB development may exert common effects." (PMID 34154646, 2021). "The same might hold true for components of the cytoskeleton, since TUBB, ACTB, and ACTG1 are all included in the candidate gene list, which would be in line with the frequently observed increased expression of cytoskeletal proteins in cancer and associations with poor outcome and chemoresistance." (PMID 40694850, 2025). "Besides, TUBB may take part in metabolic disorder processes in cancers." (PMID 38756529, 2024). "In SARC, the TUBB mRNA expression level was negatively related to the abundance of B cells and CD8+ T which are both strongly immune-related cells and pivotal targets for cancer therapies." (PMID 38756529, 2024). "Similarly, the expression of SLC3A2, TUBA1B, TUBA1C, TUBB, FSTL1, and INSIG1 was affected by FIRΔexon2, suggesting that FIR and FIRΔexon2 engage in the transcription of various cancer-related mRNAs." (PMID 38139171, 2023). "The carnitine system is related to cancer metabolic plasticity and acetylation of carnitine facilitates myelination of regenerated axons after peripheral nerve injuries with physical binding to PMP2 and TUBB." (PMID 33228226, 2020). "At present, the role of TUBB has not been ascertained in cancers." (PMID 38756529, 2024). "We analyzed the correlations between z-scores of 14 symbolic functional states of cancers (angiogenesis, apoptosis, cell cycle, differentiation, DNA damage, DNA repair, EMT, hypoxia, inflammation, invasion, metastasis, proliferation, quiescence, stemness) with the z-score of TUBB expressions." (PMID 38756529, 2024). "In SARC, the TUBB mRNA expression level was negatively related to the abundance of B cells and CD8+ T cells across different software, which could possibly explain why TUBB was risky in cancers." (PMID 38756529, 2024). "In addition, MTlo cancer cells expressed higher levels of SMTN1, TUBB, TUBA1A, and TUBA1B genes involved in microtubule turnover which contributes to cellular processes such as intracellular transport, cell division and migration, than MThi cancer cells did." (PMID 34483138, 2021). "Among the set of genes that we identify as being related to RCC, some were known from previous studies (e.g. ATP6V1B1, EGLN3, SLC25A5, TUBB, ALDOA); others had never before been associated with RCC, but have been identified with other cancers (e.g. ABL2, JAZF1, TFAP2A)." (PMID 19455236, 2007). "However, the exact role of TUBB in pan-cancers has not been illustrated." (PMID 38756529, 2024).